MBOAT7 (membrane bound acylglycerophosphatidylinositol O-acyltransferase MBOAT7)
Diseases named in the same sentence as MBOAT7 in open-access papers (continued):
Sharing a sentence is not in itself a finding about the gene and the disease.
COVID-19 (2 papers, 2022 to 2024). A disease caused by infection with severe acute respiratory syndrome coronavirus 2. "In conclusion, the present study results demonstrated significant association of circulating MBOAT7 protein, MBOAT7 mRNA expression with the level of inflammation, severity, and outcome in COVID-19 patients." (PMID 38183501, 2024). "Interestingly, polymorphism in the MBOAT7 gene was associated with severe liver injury in hospitalized COVID-19 patients." (PMID 38183501, 2024). "MBOAT7 was reported to negatively regulate Toll-like receptors (TLRs) signaling in both metabolic-associated fatty liver disease (MAFLD) and COVID-19." (PMID 38183501, 2024). "MBOAT7 mRNA and protein levels were significantly downregulated in COVID-19 patients group compared to controls (p < 0.0001)." (PMID 38183501, 2024). "Significant lower levels of circulating MBOAT7 mRNA and protein were observed in COVID-19 patients compared to control subjects with severe COVID-19 cases showing significant lower levels compared to moderate cases." (PMID 38183501, 2024). "We aimed in this study to evaluate MBOAT7 expression in COVID-19 patients and to correlate it with disease severity and outcomes." (PMID 38183501, 2024). "In the present study, we found that MBOAT7 was significantly downregulated in COVID-19 patients compared to healthy controls." (PMID 38183501, 2024). "The possible role of circulating plasma MBOAT7 protein level in predicting COVID-19 is illustrated in." (PMID 38183501, 2024). "MBOAT7 deficiency in macrophages as observed in patients with MAFLD and in COVID-19, alters membrane phospholipid composition." (PMID 36473860, 2022). "MBOAT7 expression was significantly downregulated in immune cells from patients with severe COVID-19 compared to healthy patients, particularly in macrophages." (PMID 36473860, 2022). "The expression pattern of MBOAT7 was significantly decreased in PMBCs of patients with COVID-19 and this was even more profound among those with severe COVID-19." (PMID 36473860, 2022). "In addition, we found that circulating MBOAT7 plasma levels were lower in severe COVID-19 cases compared to moderate cases." (PMID 38183501, 2024). "In addition, MBOAT7 expression was downregulated with the severity of COVID-19 in the Mono_c1-CD14-CCL3 subtype of monocytes." (PMID 36473860, 2022). "Since studies identified PLA2 inhibitors as therapeutic targets to reduce COVID-19 mortality, future research could address therapy that upregulates MBOAT7 activity as a complimentary strategy to inhibitors of PLA2 in order to restore normal Lands’ cycle homeostasis and minimize inflammation or CS." (PMID 38183501, 2024). "Our findings highlight that modulation of MBOAT7 may provide therapeutic benefit for suppressing inflammation in human diseases associated with dysregulation of the TLR signalling cascade, including in COVID-19 and MAFLD." (PMID 36473860, 2022). "MBOAT7 expression is reduced in both patients with MAFLD and COVID-19 and in human macrophages after TLRs and SARS-CoV-2 stimulation." (PMID 36473860, 2022). "Here the authors report that MBOAT7 is reduced in macrophages of patients with MAFLD and COVID-19, and acts as a negative regulator of TLR signalling." (PMID 36473860, 2022). "To date, MBOAT7 has not been extensively investigated in COVID-19, hence in the present study, we aimed to evaluate MBOAT7 expression in COVID-19 patients and to correlate the levels of this anti-inflammatory enzyme with disease severity and outcomes." (PMID 38183501, 2024). "However, to date, the role of MBOAT7 in COVID-19 has not been evaluated." (PMID 38183501, 2024). "Thus, to determine whether MBOAT7 plays a role in SARS-CoV-2-induced inflammatory responses, we reanalyzed a publicly available dataset for MBOAT7 expression in immune cells from patients with differing severities of COVID-19." (PMID 36473860, 2022).
developmental delay (2 papers, 2019 to 2022). "Our findings highlight the MBOAT7 c.758_778del variant as a cause of developmental delay/ID in the Pakistani population, and broaden knowledge of the phenotypical outcomes associated with MBOAT7 gene variants." (PMID 31852446, 2019). "All patients with MBOAT7 variants showed infantile hypotonia and developmental delay in common." (PMID 35509994, 2022).
microcephaly (2 papers, 2022 to 2026). A congenital or acquired developmental disorder in which the circumference of the head is smaller than normal for the person's age and sex. "Our findings provide mechanistic insights not only into microcephaly associated with MBOAT7 deficiency but also into the importance of arachidonic acid in embryonic brain development." (PMID 41488780, 2026). "A recent study proposed that impaired migration and increased apoptosis induced by lysoPI-mTOR signaling in IPCs underlie microcephaly associated with MBOAT7 deficiency." (PMID 41488780, 2026). "Notably, patients harboring null mutations in MBOAT7 show severe intellectual disability, epilepsy, autistic features, and microcephaly." (PMID 41488780, 2026). "Thus, impaired RGC integrity might contribute not only to microcephaly but also to the neuronal migration defects observed in MBOAT7 deficiency." (PMID 41488780, 2026). "This enrichment is mediated by the phospholipid remodeling enzyme lysophospholipid acyltransferase 11 (LPLAT11), also known as membrane-bound O-acyltransferase 7 (MBOAT7), whose deficiency causes microcephaly in both humans and mice." (PMID 41488780, 2026). "The fact that null mutations in MBOAT7, whose product LPLAT11 is responsible for incorporating arachidonic acid into PI, cause microcephaly both in humans and mice points to a crucial role for arachidonic acid in PI during cortical development." (PMID 41488780, 2026). ",48Mboat7-Sox1-KO mice exhibited microcephaly similar to that in Mboat7 KO mice." (PMID 41488780, 2026).
polymicrogyria (2 papers, 2022 to 2026). A developmental brain abnormality characterized by an excessive amount of small convolutions on the surface of the brain and cognitive dysfunction. "Consistently, patients harboring null mutations in MBOAT7 exhibit polymicrogyria, a condition thought to result from aberrant neuronal migration." (PMID 41488780, 2026). "In that report, most patients carrying MBOAT7 variants showed normal brain MRIs, except for two patients with brain atrophy and mild polymicrogyria." (PMID 35509994, 2022).
renal carcinoma (2 papers, 2021 to 2023). A carcinoma arising from the epithelium of the renal parenchyma or the renal pelvis. "In contrast, increased MBOAT7 expression is linked to hepatocellular and renal cancers." (PMID 37316513, 2023). "MBOAT7 was overexpressed in renal cancer cells and high MBOAT7 expression was associated with poor prognosis in ccRCC.CCDC58 may play a tumor-promoting role in endometrial cancer." (PMID 34706720, 2021).
venous thromboembolism (2 papers, 2019 to 2021). Occlusion of the lumen of a vein by a thrombus that has migrated from a distal site via the blood stream. "Among other genetic variants related to NAFLD, TM6SF2 appears to be protective, whereas MBOAT7 could favor venous thromboembolism." (PMID 34798835, 2021). "These included novel associations of variants at COL5A1 with cerebrovascular disease (P = 4.6 × 10−4), GALNT16 with angina (P = 9.3 × 10−4), MBOAT7 with venous thromboembolism (P = 1.3 × 10−3), GLTPD2 with atherosclerosis (P = 5.3 × 10−4) and SPTLC3 with intracerebral haemorrhage (P = 1.0 × 10−3)." (PMID 31551469, 2019).
alcohol abuse (1 paper, 2024). The use of alcoholic beverages to excess, either on individual occasions ("binge drinking") or as a regular practice. "Female control (Mboat7fl/fl) or hepatocyte-specific Mboat7 knockout mice (Mboat7-HSKO) were fed with subjected the NIAAA (National Institute on Alcohol Abuse and Alcoholism) model of ethanol-induced liver injury." (PMID 38648183, 2024).
chronic hepatitis C (1 paper, 2021). "Genetic variants including PNPLA3-rs738409 C>G, TM6SF2-rs58542926 C>T, MBOAT7-rs641738 C>T, and HSD17B13-rs72613567 T>TA have been shown to influence progression to advanced chronic liver disease (ACLD) in patients with chronic hepatitis C (CHC)." (PMID 33917196, 2021).
clear cell renal carcinoma (1 paper, 2023). A malignant epithelial neoplasm of the kidney characterized by the presence of lipid-containing clear cells within a vascular network. "High expression of MBOAT7 has been detected in multiple types of cancer, and studies of clear cell renal carcinoma suggest MBOAT7 inhibition as a possible therapy." (PMID 37316513, 2023).
coronary heart disease (1 paper, 2022). "We hypothesized that MBOAT7 may be a key link between NAFLD and coronary heart disease, and investigated both changes in MBOAT7 expression in peripheral blood leukocytes after AMI and the possible molecular mechanisms in hepatocytes." (PMID 35582424, 2022).
gastrointestinal stromal tumor (1 paper, 2018). "As positive control tissues, we included a sample of testis and a sample of gastrointestinal stromal tumor retrieved from the collection of our Pathology Department in which we observed a strong immunoreactivity of MBOAT7." (PMID 29572551, 2018).
hemochromatosis (1 paper, 2021). A disorder of iron metabolism characterized by a triad of HEMOSIDEROSIS; LIVER CIRRHOSIS; and DIABETES MELLITUS. "Two more gene variants were shown to contribute to HCC development: hemochromatosis (HFE) H63D gene and the rs641738 genotype encoding membrane-bound O-acyltransferase domain-containing 7 (MBOAT7)." (PMID 34830997, 2021).
papillary carcinoma (1 paper, 2022). A malignant epithelial neoplasm characterized by a papillary growth pattern. "The results revealed that metabolism-related pathways, such as oxidative phosphorylation and glycerophospholipid metabolism (PCYT2, MBOAT7, DGKA, etc.), were enriched in papillary carcinoma." (PMID 35659036, 2022).
sarcopenia (1 paper, 2025). Progressive decline in muscle mass due to aging which results in decreased functional capacity of muscles. "It is characterized by visceral obesity, sarcopenia, and significant genetic determinants (variants of PNPLA3, TM6SF2, and MBOAT7) in normal BMI individuals." (PMID 41189623, 2025).
cancer (7 papers, 2015 to 2024). A tumor composed of atypical neoplastic, often pleomorphic cells that invade other tissues. "However, in some cancers, this downregulation of MBOAT7 expression may be associated with increased tumorigenesis." (PMID 38893234, 2024). "In the tumors of these cancers, MBOAT7 is upregulated compared to healthy tissues, which is associated with a worse prognosis." (PMID 38893234, 2024). "Although MBOAT7 likely plays unique roles in different cancer types, additional studies are warranted to understand the mechanisms by which MBOAT7 may shape key signaling lipids within the tumor microenvironment." (PMID 35636492, 2022). "The GEPIA data indicate that MBOAT7 may be an interesting therapeutic target for cancer treatment." (PMID 38893234, 2024). "The roles of UAP1, HEATR2, and MBOAT7 in cancer remains unclear." (PMID 25577646, 2015).
metabolic disease (6 papers, 2019 to 2025). A congenital disorder (due to inherited enzyme abnormality) or acquired (due to failure of a metabolically important organ) disorder resulting from an abnormal metabolic process. "Interestingly both protein products of MBOAT7 and HEXB genes are involved in metabolic disorders of lipid biosynthesis and remodeling within the brain, and this group of disorders are an important and often overlooked consideration in the differential diagnosis of neurodevelopmental disorders." (PMID 31852446, 2019).
tumor (6 papers, 2020 to 2023). "A previous report in April 2020 showed that the MBOAT7 gene could be restricted to reduce the content of arachidonic acid-containing phosphatidylinositol pools in KIRC by altering the lipid metabolism of tumor cells, thereby producing a therapeutic effect." (PMID 35846357, 2022).
neurodevelopmental disorder (4 papers, 2019 to 2026). A behavioral and cognitive disorder with onset during the developmental period that involves impaired or aberrant development of intellectual, motor, or social functions. "In a global study of patients with neurodevelopmental disorders, a significant number of patients had biallelic or pathogenic variants in LPIAT1 or MBOAT7." (PMID 37250116, 2023). "In this study, molecular modeling of the variant protein revealed the molecular pathomechanism of a novel variant of MBOAT7 (c.757G>A, p.Glu253Lys) in neurodevelopmental disorders." (PMID 35509994, 2022). "This study consolidates variation within MBOAT7 as a cause of neurodevelopmental disorder, broadens knowledge of the clinical outcomes associated with MBOAT7-related disorder, and confirms the likely presence of a regionally prevalent founder variant (c.758_778del; p.Glu253_Ala259del) in Pakistan." (PMID 31852446, 2019).
cardiovascular disease (1 paper, 2025). "Previous work has suggested that MBOAT7 rs641738 C > T has a relatively minor impact on cardiovascular disease, in spite of its known mechanistic association with an increased accumulation of free arachidonic acid (a precursor of proinflammatory lipid mediators)." (PMID 40868230, 2025).
infectious disease (1 paper, 2022). A disorder directly resulting from the presence and activity of a microbial, viral, or parasitic agent in humans. "The dominant effect of MBOAT7 downregulation on liver rather than infectious diseases might be explained by the multiple hits implicated in MAFLD pathogenesis that might be regulated by MBOAT7 including TRL signalling and increases in liver fat content." (PMID 36473860, 2022).
inflammation (1 paper, 2016). Aberrant reaction of the microcirculation characterized by movement of fluid and leukocytes from the blood into extravascular tissues. "In a further analysis, MBOAT7 expression was significantly higher in subjects with none or mild hepatic inflammation (A0–A1), compared with those with significant hepatic inflammation (A2–A3)." (PMID 27630043, 2016).
kidney disease (1 paper, 2025). "Additionally, genetic variants such as PNPLA3, TM6SF2, and MBOAT7 were identified as contributing to both liver and kidney disease, increasing cardiometabolic risk." (PMID 40217935, 2025).
mitochondrial disease (1 paper, 2025). "Since MASLD occurs as a mitochondrial disease and the PNPLA3, MBOAT7 and TM6SF2 loss-of-function mutations seem to achieve a role in organelles’ dysfunction, in this study, we firstly investigated the impact of gene deletion on mitochondrial dynamism and integrity in KO HepG2 cells." (PMID 40563253, 2025).
MBOAT7 also shares sentences with these, for which no sentence is quoted: non-alcoholic steatohepatitis (6 papers); type 2 diabetes (4); diabetes (3); metabolic syndrome (3); neurological diseases (3); autism spectrum disorder (2); colorectal cancer (2); liver (2); lung carcinoma (2); non-small cell lung carcinoma (2); acute myocardial infarction (1); alcoholic fatty liver disease (1); Alcoholism (1); all (1); angina (1); atherosclerosis (1); autism (1); autoimmune conditions (1); Brain atrophy (1); cerebrovascular disease (1); cervical cancer (1); chronic hepatitis B (1); endometrial cancer (1); hepatitis B (1); Hydrocephalus (1); intracerebral haemorrhage (1); lung adenocarcinoma (1); paraplegia (1); portal hypertension (1).